RAB42 (RAB42, member RAS oncogene family)
Description:
The small GTPases Rab are key regulators of intracellular membrane trafficking, from the formation of transport vesicles to their fusion with membranes. Rabs cycle between an inactive GDP-bound form and an active GTP-bound form that is able to recruit to membranes different sets of downstream effectors directly responsible for vesicle formation, movement, tethering and fusion (By similarity). The physiological function of RAB42 remains undefined (Probable).
Synonyms: MGC45806
Tractability: Antibody: its Gene Ontology location is reachable by antibodies, with medium confidence. PROTAC: ubiquitination databases record sites on it.
Gene: Protein-coding gene on chromosome 1 (28,592,200 to 28,595,449, forward strand). Ensembl gene ENSG00000188060.
Subcellular location: Membrane
Subcellular location (Human Protein Atlas): Endoplasmic reticulum
Pathways (Reactome):
Metabolism of proteins: RAB geranylgeranylation
Gene Ontology:
Molecular function: GTPase activity; G protein activity; GTP binding
Biological process: small GTPase-mediated signal transduction
Cellular component: membrane; plasma membrane
Genetic constraint (gnomAD): Loss-of-function variants: 8 observed, 6.48 expected, observed/expected ratio (o/e) 1.23, 90% interval 0.71 to 1.87. That is too few expected variants to judge how well the gene tolerates losing a copy. Missense variants: 200 observed, 253.36 expected, observed/expected ratio (o/e) 0.79, 90% interval 0.7 to 0.89. Synonymous variants: 79 observed, 112.67 expected, observed/expected ratio (o/e) 0.7, 90% interval 0.58 to 0.85.
Homologues: Orthologues: chimpanzee RAB42 (99% identical), macaque RAB42 (98% identical), rabbit RAB42 (89% identical), dog RAB42 (88% identical), pig RAB42 (88% identical), rat Rab42 (80% identical), mouse Rab42 (78% identical), guinea pig RAB42 (76% identical). Paralogues in human: RAB39A (45% identical), RAB39B (42% identical), RAB1A (33% identical), RAB1B (33% identical), RAB11A (33% identical), RAB30 (33% identical), RAB11B (32% identical), RAB26 (32% identical), RAB2B (32% identical), RAB43 (32% identical), RAB25 (32% identical), RAB8A (32% identical), and 56 more.
Diseases named in the same sentence as RAB42 in open-access papers:
RAB42 is named in the same sentence as 32 diseases in open-access papers, as found by Europe PMC text mining. Sharing a sentence is not in itself a finding about the gene and the disease. The quoted sentences say what the papers report.
glioma (9 papers, 2021 to 2024). A benign or malignant brain and spinal cord tumor that arises from glial cells (astrocytes, oligodendrocytes, ependymal cells). "It has been reported that RAB42 is negatively associated with 5-year overall survival and shows a poorer prognosis in glioma patients." (PMID 35741652, 2022). "Subsequently, we experimentally validated that RAB42 promoted the proliferation, migration and invasion of glioma and the pro-oncogenic mechanism of RAB42 is associated with the activation of VEGF signaling pathways." (PMID 34912698, 2021). "As a novel tumor biomarker, RAB42 is associated with poor prognosis in glioma." (PMID 36671428, 2022). "A recent study revealed that RAB42 expression in glioma was negatively related to the 5-year overall survival rate, which can be used as a risk factor to predict the poor prognosis of patients with glioma." (PMID 35720121, 2022). "Previous studies have reported that RAB42 is associated with prognosis and progression in glioma." (PMID 35720121, 2022). "Furthermore, functional in vitro experiments indicated that RAB42 promoted the proliferation, migration and invasion of glioma and the pro-oncogenic mechanism of RAB42 is associated with the activation of VEGF signaling pathways." (PMID 34912698, 2021). "A few studies demonstrated that RAB42 is expressed in mucinous lung adenocarcinoma, breast cancer, glioma, and LIHC." (PMID 39101146, 2024). "By screening differentially expressed genes, and performing WGCNA, LASSO, and multivariate Cox regression analyses, we identified risk hub genes (RAB42, SH2D4A, and GDF15) associated with glioma stemness, genomic heterogeneity, and the immune microenvironment." (PMID 37698534, 2023). "Studies have shown that RAB42 can promote the proliferation, migration and invasion of glioma cells." (PMID 37698534, 2023). "The expression of three risk hub genes in glioma was investigated in the TCGA and CGGA datasets, and RAB42, SH2D4A, and GDF15 were found to be higher expressed in GBM than in LGG." (PMID 37698534, 2023). "RAB42 is a member of the mammalian Rab family of small GTPases and has been attributed to prognosis in glioma patients." (PMID 37091145, 2023). "A previous study confirmed that RAB42 overexpression served as an indicator of poor prognosis for glioma patients." (PMID 36671428, 2022). "The research in glioma first demonstrated that RAB42 was negatively correlated with 5-year OS and displayed a poorer prognosis." (PMID 35741652, 2022). "Similar to previous studies, our findings indicated that RAB42 functioned as an oncogene in glioma, activated VEGF signaling pathways, and regulated PI3K/AKT signal axis." (PMID 34912698, 2021). "Meanwhile, a PCR microarray was performed to investigate genetic alterations in VEGF signaling pathway after RAB42 knockdown in glioma." (PMID 34912698, 2021). "Survival analysis indicated that low RAB42 expression in CGGA glioma (including GBM and LGG) tissues predicted favorable survival outcome and vice versa (Kaplan-Meier survival analysis; P < 0.001)." (PMID 34912698, 2021). "To depict the accuracy of RAB42 for predicting prognostic in glioma patients, we plotted ROC curves using the data downloaded from the CGGA database." (PMID 34912698, 2021). "After a series of bioinformatics analysis and experiments in vitro, we found that RAB42 promotes glioma pathogenesis via the VEGF signaling pathway." (PMID 34912698, 2021). "Through WGCNA, LASSO and multivariate Cox regression analyses, we identified RAB42, SH2D4A and GDF15 as high-risk hub genes for glioma, and we employed these genes to create a risk model that showed high sensitivity and specificity in prognosticating patients’ 1-, 3-, and 5-year survival." (PMID 37698534, 2023). "In addition, RAB42 correlated with multiple clinical characteristics and promoted the proliferation, migration, and invasion of glioma via activating VEGF signaling pathway." (PMID 35720121, 2022).
glioma (continued). "The previous study has reported that RAB42 expression was negatively correlated with overall survival in glioma and could be used as a predictor for the prognosis of patients with glioma." (PMID 35720121, 2022). "Zhang obtained mRNA transcription information and clinical data of gliomas from the TCGA database and found that the expression of RAB42, SHOX2, IGFBP2, HIST1H3G, and IGF2BP3 negatively correlated with 5-years OS; also, IGF2BP3 expression significantly positively correlated with glioma grades." (PMID 34721530, 2021). "Results of CCK8 assays showed downregulation of RAB42 reduced cell proliferation of glioma cells." (PMID 34912698, 2021). "The results indicated that RAB42 activated VEGF signaling pathway and was associated with apoptosis, natural killer cell mediated cytotoxicity pathways and JAK-STAT signaling pathways by PI3K/AKT in gliomas." (PMID 34912698, 2021). "As shown in transwell results, RAB42 knockdown inhibited invasion and migration of glioma cells." (PMID 34912698, 2021). "Analysis of gene functions indicated that RAB42 activated VEGF signaling pathways and the mechanism was associated with natural killer cell mediated cytotoxicity, JAK-STAT signaling pathway and apoptosis pathways by PI3K/AKT in gliomas." (PMID 34912698, 2021). "This is consistent with CGGA results indicating that RAB42 could be a poor prognostic predictor in glioma." (PMID 34912698, 2021). "In conclusion, we explored the biological function of RAB42 and mechanism in glioma." (PMID 34912698, 2021). "In addition, in vitro experiments also validated that RAB42 also promoted the proliferation and invasion of glioma cells, which may be related to the activation of the VEGF pathway." (PMID 35720121, 2022). "RAB42 was still identified as an independent prognostic factor in a multivariable analysis (HR = 1.222; 95% CI= 1.100–1.357; P < 0.001), implying that it could be a powerful indicator of prognosis in glioma portending poor prognosis." (PMID 34912698, 2021). "In the TCGA and CGGA datasets, the Kaplan-Meier curve showed that RAB42, SH2D4A, and GDF15 significantly affected the prognosis of glioma, with a poor prognosis at high expression." (PMID 37698534, 2023). "Contrary, RAB42 was significantly expressed on the membrane of glioma tissues but not in normal tissues." (PMID 34912698, 2021).
glioblastoma (5 papers, 2021 to 2024). The most malignant astrocytic tumor (WHO grade IV). "In comparison to normal samples, glioblastoma (GBM) samples showed higher expression of RAB42." (PMID 36908705, 2023).
hepatocellular carcinoma (4 papers, 2022 to 2025). A malignant tumor that arises from hepatocytes. "RAB42 expression levels in hepatocellular carcinoma (HCC) tissues were higher than in normal tissues, according to a prior investigation." (PMID 36908705, 2023). "Furthermore, RAB42 is correlated with immune infiltration in hepatocellular carcinoma." (PMID 36671428, 2022). "The knockdown of Rab42 decreased proliferation, migration, and invasion in MHCC-97H hepatocellular carcinoma (HCC) cells." (PMID 40293576, 2025).
choroideremia (2 papers, 2013 to 2024). Choroideremia (CHM) is an X-linked chorioretinal dystrophy characterized by progressive degeneration of the choroid, retinal pigment epithelium (RPE) and retina. "They found that Rab38, Rab27a, Rab27b, and Rab42 are prenylated the slowest and concluded that this finding may implicate them in choroideremia, since they may be more impacted by REP-1 deficiency when only REP-2 is present." (PMID 38920696, 2024). "In conclusion, Rab27a is prenylated slowly in vivo and in vitro, but in addition also other Rabs like Rab38 and Rab42 show slow prenylation kinetics and could therefore potentially play a role in choroideremia." (PMID 24358126, 2013).
liver cancer (2 papers, 2022 to 2024). An epithelial or non-epithelial malignant neoplasm that arises from the liver. "Previous study shown that RAB42 is positively correlated with exhausted CD8+ T cells in liver cancer." (PMID 39101146, 2024). "The results showed the proportion of EdU-positive cells was significantly decreased with the transfection of siRAB42 in SMMC7721 and Hep3B cells, indicating that knockdown of RAB42 significantly inhibited the proliferation of liver cancer cells." (PMID 35720121, 2022). "Subsequently, we performed KEGG and GO enrichment analysis on these differentially co-expressed genes to explore the potential pathways of RAB42 in regulating liver cancer." (PMID 35720121, 2022). "Experiments in vitro indicated that knockdown of RAB42 inhibited the proliferation, invasion, and migration of liver cancer cells." (PMID 35720121, 2022). "Collectively, these results indicated that RAB42 was involved in the regulation of the proliferation, invasion, and migration of liver cancer cells in vitro, and the specific molecular mechanism needs to be further explored in the future." (PMID 35720121, 2022). "Then, transwell assays were performed to detect the role of RAB42 expression in regulating the invasion and migration of liver cancer cells." (PMID 35720121, 2022). "To verify the role of RAB42 in HCC in vitro, we first analyzed RAB42 mRNA expression levels in liver cancer cell lines, including SMMC7721, Huh7, MHCCLM3, MHCC97L, Hep3B, HepG2 and normal hepatic cell line, LO2." (PMID 35720121, 2022). "Therefore, we selected two liver cancer cell lines, SMMC7721 and Hep3B cells with relatively high RAB42 expression, for subsequent knockdown experiments." (PMID 35720121, 2022). "The results confirmed that RAB42 was highly expressed in liver cancer cells compared with normal liver cells." (PMID 35720121, 2022). "Few studies have investigated the role of RAB42 in tumors, to reveal the potential biological function of RAB42 in HCC, we searched the genes that co-expressed with RAB42 in liver cancer, and the functional enrichment analysis on these co-expressed genes was performed." (PMID 35720121, 2022). "However, the research of RAB42 in HCC is lacking, so we aimed to detect the expression levels of RAB42 in HCC, and to explore the relationship between RAB42 and DNA methylation status and immune cells infiltration of liver cancer by employing available databases." (PMID 35720121, 2022).
thyroid cancer (2 papers, 2017 to 2022). "Additionally, a positive correlation between RAB42 expression and TMB was exhibited in breast invasive carcinoma (BRCA), COAD, LGG, LUAD, OV and SARC, while a negative correlation was found in HNSC, SKCM, thyroid carcinoma (THCA) and thymoma (THYM)." (PMID 36671428, 2022).
candidiasis (1 paper, 2021). Infection with the organism Candida. "Interestingly, we showed that genetic variation in close vicinity of the phagocytosis/phagosome maturation-associated genes ASGR2, LAMP1, RAB42, GEM, ATP6V1B2, and RAB20 are associated with susceptibility to candidiasis." (PMID 33510868, 2021).
colorectal cancer (1 paper, 2022). A primary or metastatic malignant neoplasm that affects the colon or rectum. "Therefore, RAB42 might be a powerful factor to assess whether colorectal cancer patients are absolutely suitable for immunotherapy." (PMID 36671428, 2022).
gastric cancer (1 paper, 2022). A primary or metastatic malignant neoplasm involving the stomach. "QPCR assays suggested that RAB42 expression was upregulated in gastric cancer cells." (PMID 36671428, 2022).
kidney cancer (1 paper, 2022). Primary or metastatic malignant neoplasm involving the kidney. "RAB42 was differentially expressed among tumor cell lines and the highest expression levels of RAB42 were found in kidney cancer cell lines." (PMID 36671428, 2022).
melanoma (1 paper, 2022). A malignant, usually aggressive tumor composed of atypical, neoplastic melanocytes. "The TIDE database showed that the patients with high-expressed RAB42 had a better prognosis treated with PD1 or CTLA4 inhibitors in melanoma (dbGaP Study Accession: phs000452.v3.p1)." (PMID 36671428, 2022).
retinal degeneration (1 paper, 2019). Degeneration of the retina. "The function of Rab42 is unclear and further Rabs may be underprenylated in RPE cells resulting in subtle defects in membrane traffic pathways, the results of which accumulate over time leading to gradual retinal degeneration." (PMID 31194861, 2019).
skin cutaneous melanoma (1 paper, 2022). "Additionally, RAB42 expression was observed to be positively related to MSI in BLCA, COAD and Sarcoma (SARC), while negatively related to MSI in HNSC, LUSC, skin cutaneous melanoma (SKCM), STAD and testicular germ cell tumors (TGCT)." (PMID 36671428, 2022).
uterine cancer (1 paper, 2024). Primary or metastatic malignant neoplasm involving the uterine corpus and/or the cervix. "This phenomena suggests that targeting RAB42 might well improve the therapeutic efficiency of carboplatin plus paclitaxel in uterine cancer." (PMID 39101146, 2024).
tumor (8 papers, 2013 to 2025). "The expression of Rab42 was linked to an increased cell infiltration of M2 macrophages and Treg cells to the tumour microenvironment and immune checkpoint molecules." (PMID 40293576, 2025). "We noticed that RAB42 was significantly associated with some anti-tumor immune cells, such as CD8+ T cells." (PMID 35720121, 2022). "We identified abundant H3K27ac signal in the RAB42 gene loci in different tumor cells by ChIP-seq data from the ENCODE database." (PMID 36671428, 2022). "Another two works have suggested that RAB42 may act as a pro-oncogene that drives tumor progression and may be a new target associated with immunotherapy in certain tumor types." (PMID 39101146, 2024). "In brief, RAB42 could serve as a diagnostic and prognostic biomarker in many tumor types." (PMID 36671428, 2022). "RAB42 could serve as a diagnostic and prognostic biomarker in many tumor types." (PMID 36671428, 2022). "The conclusions of this study are as follows.Rab proteins (i.e., Rab9 and Rab42) promote tumour progression by influencing trafficking and interacting with other proteins and pathways (e.g., p40, E2F1, immune tolerance, and checkpoint proteins)." (PMID 40293576, 2025). "The significant correlation between RAB42 overexpression and Treg cell level implies that RAB42 plays an essential role in tumor microenvironment." (PMID 39101146, 2024). "RAB42 overexpression also correlates with enhanced RNA modifications, poor tumor immune cell infiltration, and declined expression of immune checkpoint genes in cancers that are non-response to immune checkpoint inhibitors (ICIs)." (PMID 39101146, 2024). "The prognostic, immunomodulatory and tumor-promoting effects of RAB42 were verified in various malignancies and determined by a series of in vitro cellular experiments." (PMID 39101146, 2024). "The analysis of the correlation between RAB42 expression and immune cells implied a possible interaction between RAB42 and the tumor microenvironment." (PMID 36671428, 2022). "As expected, we confirmed that RAB42 expression was positively correlated with immune checkpoint gene expression in most tumor types." (PMID 36671428, 2022). "By comparing RAB42 mRNA levels in tumor and normal tissues using the SangerBox, ACLBI, TIMER2.0 and UALCAN databases, we observed the upregulated expression of RAB42 in most tumor tissues." (PMID 36671428, 2022). "RAB42 significantly positively correlated with the gene markers of CD8+ T cells, Th1 cells, Th2 cells, Tfh cells, Th17 cells, Treg cells, tumor-associated macrophages (TAM), M1 macrophages, M2 macrophages, neutrophils cells, NK cells, DCs and B cells." (PMID 35720121, 2022). "In the present study, RAB42 showed cancer-promoting functions by regulating multiple tumor-related signaling pathways, which is consistent with previous findings." (PMID 34912698, 2021). "Rab42 promoted tumour proliferation, and migration and triggered immunotolerance." (PMID 40293576, 2025). "Moreover, the risk signature and risk hub genes RAB42, SH2D4A, and GDF15 were highly positively correlated with the increase of these immunosuppressive tumor infiltrating cells." (PMID 37698534, 2023). "Moreover, the RAB42 expression remarkably correlated with tumor stage, histologic grade, and patients’ age, and the advanced HCC patients tend to have higher expression of RAB42." (PMID 35720121, 2022). "Our results also demonstrated that RAB42 expression was correlated with tumor pathologic stages." (PMID 36671428, 2022). "The alteration frequency of RAB42 was less than 3% in most tumor types." (PMID 36671428, 2022). "We evaluated RAB42 expression in tumor cell lines from 21 tumor tissues." (PMID 36671428, 2022). "The correlation between RAB42 expression and tumor lymphocyte infiltration in HCC (TISIDB)." (PMID 35720121, 2022). "Using the data in TCGA, the RAB42 expression in GBM tumor tissues and normal tissues was compared." (PMID 35741652, 2022).